VIM (vimentin)
Diseases named in the same sentence as VIM in open-access papers (continued):
Sharing a sentence is not in itself a finding about the gene and the disease.
cancer (continued). "Aberrant activation of EMT is crucial in cancer metastasis and involves multiple molecular mechanisms and signal transduction pathways, the hallmark of which is the downregulation of E-cadherin and upregulation of vimentin." (PMID 37509669, 2023). "The epithelial-to-mesenchymal transition (EMT) is an acute event in cancer metastasis, characterized by reciprocal loss of expression of epithelial cell-associated proteins, such as E-cadherin, and increased levels of mesenchymal markers, such as vimentin." (PMID 36979779, 2023). "Vimentin (VIM) is (over)expressed in several carcinomas, putatively in association with EMT." (PMID 36594099, 2023). "Moreover, the number of cancer cells (stained positive for human vimentin) was significantly associated with the number of OPs/osteoclasts (stained positive for RANK) in the bone." (PMID 34847079, 2022). "Cancer-associated fibroblasts (CAFs) are large, spindle-shaped mesenchymal cells that share characteristics with smooth muscle cells and fibroblasts, including the expression of both vimentin and α-SMA." (PMID 35300411, 2022). "High expression of vimentin is a hallmark of many types of cancer cells." (PMID 36099296, 2022). "With these observations, we can speculate that the expression of vimentin regulates the initial steps of the EMT associated with cancer metastasis/progression." (PMID 36200046, 2022). "Similarly, the enhanced expression of VIM was associated with the increased migration and invasion of cancer cells." (PMID 36013233, 2022). "We found a significant association of the vimentin expression in oral precancers and cancers." (PMID 35498535, 2022). "This suggests that the association between vimentin and risk factors may show variation depending upon the site of origin of cancer." (PMID 35207438, 2022). "First, we investigated whether changes in vimentin of cancer cells caused by NK cells could be detected in cancer patients." (PMID 36032170, 2022). "Some examples are PTPN11 that is known to activate a transcriptional program associated with cancer stem cells or the EMT-related genes SOX4 or VIM that might be responsible for the high invasive capacity of the tumors and their early metastasis formation." (PMID 33706810, 2021). "Several missense and frameshift mutations reported in vimentin in human cancers may also contribute towards the metastatic spread." (PMID 34638469, 2021). "Furthermore, the loss-of-function of VIM across primary and metastatic cell lines can be explored to interrogate gene effect across cancer types." (PMID 33299129, 2021). "Intermediate filaments vimentin and nestin are associated with different types of cancer." (PMID 33919917, 2021). "Vimentin+ cells likely represent carcinoma associated fibroblasts." (PMID 34290694, 2021). "The exchange of CK7 for vimentin could be associated with EMT by the fact that vimentin gives carcinoma cells more flexibility to change cell shape and, thus, better adapt for migration." (PMID 34198671, 2021). "Vimentin can serve as a potential diagnostic tool for detecting cancer." (PMID 32670437, 2020). "EMT, a hallmark of aggressive and highly invasive cancers, contributes to CisR in OC cells by suppressing the epithelial marker (E-cadherin) and enhancing the expression of mesenchymal marker proteins (N-cadherin and vimentin)." (PMID 33076245, 2020). "In parallel, following exposure to H. pylori, changes were evident in levels of mRNA expression of epithelial to mesenchymal transition (EMT)-encoding factors including snail, slug, vimentin, matrix metalloprotease, zinc finger E-box-binding homeobox, and the cancer stem cell marker CD44." (PMID 33233485, 2020). "Vimentin is also required for cancer-associated fibroblasts motility leading to EMT." (PMID 33171868, 2020).
cancer (continued). "The growing significance of EMT in the tumorigenesis of various cancers has been the subject of studies these years, and the main features comprise a loss of the epithelial markers E-cadherin and increase of the mesenchymal markers N-cadherin and Vimentin." (PMID 33117668, 2020). "Moreover, previous studies on different types of human carcinomas have shown that loss of E-cadherin and β-catenin, in addition to enhanced expression of vimentin and fascin, can promote EMT, which is associated with cancer progression." (PMID 32947764, 2020). "Finally, TCGA (The Cancer Genome Atlas) analysis also supported the association of NgR and vimentin." (PMID 31649250, 2019). "Notably, EMT markers changed during cancer progression, specifically with loss of E-cadherin and increase of vimentin, but these changes were significantly attenuated by baicalein." (PMID 31000696, 2019). "Indeed, we found that artificial overexpression of vimentin in both cancer cell lines caused enhanced migration up to 130%." (PMID 30894168, 2019). "Although EMT has been demonstrated to participate in VM in a variety of cancers, the role of Vimentin underling this mediating process in RCC remains unknown." (PMID 31428643, 2019). "As the loss of E-cadherin and/or increase in vimentin expression were expected features of cancer progression, those results suggested that hypoxia triggers - to a certain extend and for the three cell lines tested – changes in expression associated with increased invasiveness." (PMID 30560881, 2018). "The initial observations that the expression of the vimentin gene was mainly observed in proliferative and undifferentiated cells were followed by studies that together indicate that vimentin is linked to the malignant transformation and metastatic spread of cancer cells." (PMID 30248895, 2018). "Taken together these data suggest that human primary OECs display significant increases in the expression of MMPs and Vimentin which are largely associated with metastatic potential in cancers and promote a migratory phenotype in the host cells during extended period of infection by P. gingival is." (PMID 29250491, 2017). "After cancer cells were exposed to IL-6 for 24 h, a spindle-shaped morphology was observed, and a near complete loss of epithelial features occurred, including E-cadherin, and increased expression of vimentin, α-SMA and N-cadherin was detected." (PMID 28846080, 2017). "Vimentin overexpression has also been associated with increased cancer cell growth, invasion, and migration, suggesting that vimentin participates in the promotion of these tumorigenic events and would serve as an effective target for cancer therapy." (PMID 27713131, 2016). "While inducing expression of BRM to slow cell growth might be considered desirable, increased expression of vimentin is associated with a more motile and invasive mesenchymal-like cancer cell phenotype." (PMID 27188282, 2016). "These hallmarks of EMT in cancers include the loss of E-cadherin expression, reduction of tight junction proteins [such as zona occludens-1 (ZO-1)] and cytokeratin, and increase of mesenchymal markers, such as vimentin, fibronectin, and N-cadherin." (PMID 27661009, 2016). "We chose these biomarkers for CTC characterization, because EpCAM and CK are commonly used for epithelial CTC detection, and previous studies have demonstrated that the expression of the mesenchymal markers twist or vimentin in CTCs is associated with cancer metastasis." (PMID 25909322, 2015). "However, the authors observed that the up-regulation of stromal vimentin, periostin, and versican is associated with higher cancer grades." (PMID 25852822, 2015). "VIMENTIN is ubiquitously expressed in normal mesenchymal cells and its overexpression is frequently associated with increased migratory and invasive capacity of cancer cells." (PMID 26185996, 2015).
cancer (continued). "Since vimentin was proved to be a regulator of cell adhesion by affecting formation and turnover adhesion structures and associated with cancer migration, we speculate vimentin may be a potential downstream protein of UBE2T in UBE2T-induced EMT and metastasis." (PMID 26308072, 2015). "Moreover, deregulated expression and/or activation of MMPs, podoplanin, p21Rac1, and/or vimentin are often associated with poor prognosis in many cancers." (PMID 24598827, 2014). "Epithelial-to-mesenchymal transition (EMT) is known to be associated with the generation of cancer stem cell-like cells, toward this end, we examined the five samples for the expression of cytokeratin and vimentin, markers for epithelial cells and mesenchymal cells, respectively." (PMID 24348907, 2013). "The intermediate filament (IF) vimentin has been implicated in cancer invasion and metastasis." (PMID 24282534, 2013). "Someone raised, A modified vimentin histologic score (M-VHS) could be an effective diagnostic tool for this cancer, as to whether can be applied to clinical needs further large-scale studies." (PMID 24088577, 2013). "Moreover, WA not only suppressed levels of the tumorigenesis and metastasis-associated vimentin protein, it also caused elevated levels of cancer cell inhibitory, extra cellular matrix-associated TIMP2 protein." (PMID 22912669, 2012). "The epithelial to mesenchymal transition (EMT) is a key process contributing to cancer metastasis, characterized by the loss of the epithelial marker E-cadherin, an increase in the mesenchymal markers Vimentin and N-cadherin, and an increase in the migratory and invasive behavior." (PMID 21851624, 2011). "Although vimentin expression is associated with poor differentiation in cancers, in our series vimentin expression is still an independent predictor of outcome after accounting for the degree of differentiation suggesting vimentin expression is a marker for more than differentiation." (PMID 21448168, 2011). "Moreover, upregulation of vimentin is linked to a migratory phenotype in cancer cells." (PMID 40806251, 2025). "Furthermore, the abundance of vimentin in cancer is associated with malignancy." (PMID 39337406, 2024). "This process takes place as cancer develops, and it involves a decrease in the expression of molecules associated with epithelial growth, such as E-cadherin, and a rise in molecules associated with mesenchymal development, such as N-cadherin, vimentin (VIM), and fibronectin (FN1)." (PMID 37397377, 2023). "Nonetheless, while phosphorylation by several tyrosine kinases and SUMO 2/3 modifications of vimentin plays a key role in promoting cell growth and migration, mechanisms and pathophysiological consequences of SUMOylation, O-linked glycosylation, and other PTMs in cancers remain poorly understood." (PMID 35207438, 2022). "Furthermore, the overexpression of FOXM1 leads to the acquisition of an EMT phenotype by activating the mesenchymal cell markers ZEB1, ZEB2, Snail2, E-cadherin, and vimentin, which are associated with increased spheroid-forming capacity and cancer stem cell surface markers (CD44 and EpCAM)." (PMID 36613925, 2022). "As previously reported, increased vimentin expression and loss of E-cadherin expression in the cooperative phenotype of tumor clusters results in metastasis, invasion, radio-resistance, and generation of cancer cells with stem cell-like characteristics in pancreatic cancer." (PMID 35300411, 2022). "In several cancer cell types, it is associated with the downregulation of common epithelial genes (cytokeratins, E-cadherin) and the upregulation of mesenchymal markers (vimentin, fibronectin, N-cadherin, and metastasis-associated in colon cancer-1 (MACC-1)) (Top)." (PMID 36612099, 2022). "However, given the fact that vimentin is intricately associated with so many cytoplasmic and nuclear proteins, it is very likely that these somatic mutations would have a pronounced effect on cancer progression and metastasis." (PMID 34638469, 2021).
cancer (continued). "In addition to the EGFR signaling change, there were also changes in several cancer‐associated proteins, such as vimentin; the marker of epithelial‐to‐mesenchymal transition (EMT) was upregulated in PC3 knockdown cells and the EMT regulator β‐catenin was upregulated upon EWI‐2 knockdown." (PMID 33605506, 2021). "Moreover, loss of vimentin enhanced amoeboid leader bleb-based migration of confined cancer cells." (PMID 31940801, 2020). "In addition to cancer, vimentin expression has been associated with a number of other diseases." (PMID 30248895, 2018). "EMT process has been recognized as a key contributor in cancer cell migration and metastasis, which is characterized by loss of cell adhesion, downregulation of E-cadherin expression, and acquisition of mesenchymal markers including N-cadherin and Vimentin to increase cell motility." (PMID 27423454, 2016). "In addition to vimentin, we found expression of N-cadherin in both round and spindle-shaped cell types of the low passage cells, both of which are considered markers of mesenchymal phenotype associated with the invasive properties of some cancer types." (PMID 26174772, 2015). "In addition to podoplanin, a type III intermediate filament cytoskeletal protein, vimentin, that regulates cytoskeletal interactions such as adhesion, migration and signaling, is also frequently overexpressed in invasive cancer cells and associates with metastasis and poor prognosis." (PMID 24598827, 2014). "EpH4-Snail cells exhibited coexistence of the mesenchyme-specific intermediate filament Vimentin and the epithelium-specific Cytokeratin-18, which is a typical feature of a hybrid E/M state of cancer cells." (PMID 41521893, 2026). "It is noted that vimentin expression also displays scattered staining pattern on the edge of cancer cells in 46.25% cases (37/80)." (PMID 41496085, 2026). "ROME-mediated increase in cancer cell intravasation is dependent on its direct interaction with vimentin." (PMID 41650465, 2026). "In epithelial tumors, FAP is typically expressed by cancer-associated fibroblasts (CAFs), a heterogeneous population of stromal cells characterized by markers such as FAP, α-smooth muscle actin (SMA), and vimentin." (PMID 40694103, 2026). "This post‐translational modification promotes PRMT1‐vimentin interaction and subsequent asymmetric dimethylation (aDMA) of vimentin at arginine (R64), driving cytoskeletal remodeling and metastatic competence in cancer cells." (PMID 40884268, 2025). "We also evaluated the expression patterns of EMT biomarkers like E‐cadherin, fascin, and vimentin, as a major event of cancer progression." (PMID 40468102, 2025). "Collectively, these findings demonstrate that PRMT1 facilitates cancer cell migration through R64 methylation of vimentin." (PMID 40884268, 2025). "To investigate the role of vimentin R64 aDMA in hypoxia‐induced cancer cell migration, we generated vimentin‐knockdown A549 and MDA‐MB‐231 cell lines and re‐expressed exogenous wild‐type (WT) vimentin or R64‐mutated variants (R64K and R64F)." (PMID 40884268, 2025). "This highlights vimentin’s potential as a therapeutic target for inhibiting cancer spread and improving patient outcomes." (PMID 40229242, 2025). "In terms of cancer, vimentin has been reported to regulate EMT, implicating its role in the development of tumors." (PMID 39937011, 2025). "Its upregulation across cancers was closely linked to epithelial-mesenchymal transition (EMT), as evidenced by decreased E-cadherin and increased vimentin levels." (PMID 40674376, 2025). "These cells, when activated from normal fibroblast within adipose tissue notably by cancer cells such as the 4T1 breast cancer cell line, exhibited increased mRNA expression of fibroblast biomarker, alpha-smooth muscle actin (α-sma), vimentin, and others." (PMID 39860214, 2025).
cancer (continued). "Although some studies have identified CK- and/or vimentin (Vim)-expressing cells in blood as cancer-derived using DNA or RNA sequencing, the complexity of these methods limits their clinical utility." (PMID 39858085, 2025). "Meanwhile, vimentin offers mechanical protection to migrating cancer cells against stresses encountered during migration or spatial confinement, and is also widely recognized as a critical marker of EMT." (PMID 41149584, 2025). "Consistently, the expression of mesenchymal biomarkers N-Cadherin, Vimentin and Snail and cancer stemness biomarkers USP37, ALDH1, OCT4 and Smo/Gli-1 in BC cells was suppressed by CYT and markedly recovered by SRSF1 overexpression." (PMID 40176901, 2025). "Among the upregulated genes were those linked to cancer formation (e.g., STOX1, PEG3, XIAP) and immune cell recruitment (e.g., CCL28, VIM), suggesting a shift towards increased cellular proliferation and remodelling of the immune microenvironment." (PMID 40683913, 2025). "The presence of vimentin in cancer cells, particularly its secretion into the extracellular environment, is believed to facilitate infections by S. aureus." (PMID 40061451, 2025). "The overexpression of vimentin in these cancer cells promotes their EMT, leading to metastasis and poor prognosis." (PMID 40282554, 2025). "In this study, we tested a new cancer vaccine directed against extracellular vimentin (eVim) in client-owned dogs with visceral hemangiosarcoma (HSA)." (PMID 41009669, 2025). "Future studies on the detailed function of Vimentin+ CAFs will be beneficial to understand their specific roles in cancer development." (PMID 39780187, 2025). "When released by fibroblasts, endothelial cells, immune cells, or cancer cells, soluble forms of vimentin are secreted as extracellular vimentin (ECV)." (PMID 40346842, 2025). "The phosphorylated vimentin also strengthens its binding to 14-3-3 proteins, inhibiting pro-apoptotic signaling pathways and contributing to chemoresistance in many cancer cells." (PMID 40229242, 2025). "Through this interaction, MCs transfer biological materials into the cancer cells, as demonstrated by the transfer of Vimentin-flag (Vim-Flag) mRNA from the MCs to the CRC cells." (PMID 41039118, 2025). "Recombinant neprilysin and ECE1 inhibition led to decreased protein levels of vimentin and CD44, which are also associated to acquired stemness traits in several types of cancer." (PMID 40830989, 2025). "We found that PDACs in KCPb–/– mice at the moribund state had more mesenchymal features than those in KC and KCPb+/– mice in terms of a higher rate of vimentin-positive cancer cells." (PMID 40454484, 2025). "MP28 appears to act as a potential EMT inhibitor that disrupts vimentin expression, and ultimately inhibits cancer cell growth, invasion, and migration." (PMID 41440915, 2025). "Vimentin plays diverse roles in EMT, focal adhesion, migration, invasion, and metastasis of cancer cells, but knowledge on the function of vimentin in CAFs is limited." (PMID 39780187, 2025). "It has been observed that VPA can stimulate the expression of E‐cadherin in cancer cells and inhibit the expression of mesenchymal markers, including N‐cadherin and vimentin." (PMID 40650414, 2025). "In particular, future work will include further phenotypical characterization for example through live imaging of specific markers like vimentin or EpCAM, indicating (changes in) mesenchymal and epithelial phenotype of cancer cells." (PMID 40585039, 2025). "This review summarizes data on mAbs reactive with cell surface vimentin and their origin from lymph nodes of cancer patients." (PMID 40051499, 2025). "Other markers like HER2/neu and vimentin can also be used to target CTCs in specific cancer types and stages." (PMID 40260304, 2025). "Snail is known to downregulate CDH1 and upregulate VIM, while XBP1 has been recently linked to EMT and metastasis, impacting cancer progression and therapy outcomes." (PMID 39759848, 2025).